SOX2 (SRY-box transcription factor 2)
Diseases named in the same sentence as SOX2 in open-access papers (continued):
Sharing a sentence is not in itself a finding about the gene and the disease.
pneumocytoma (1 paper, 2020). "For these considerations, the aim of our study is to highlight the elevated expression of ALDH in the pneumocytoma of the lung as described, as well as the presence of SOX-2 markers in patients with a lymph node recurrence, and in one with a PET-positive nodule." (PMID 32984377, 2020). "Although we are conscious of the fact that our study focuses on a small number of patients, due to the rarity of this benign disease of the lung, we strongly believe that the presence of ALDH and SOX-2 in pneumocytoma of the lung requires deeper analysis, especially in patients who show recurrence." (PMID 32984377, 2020). "The involvement of SOX-2 may be crucial also for the angiogenesis in this type of tumor, synergistically participating with ALDH positive cells in the vascular impairment of pneumocytoma." (PMID 32984377, 2020).
Prader-Willi syndrome (1 paper, 2019). "Among the RNAs that interacted with the Sox2 promoter, two were derived from well-known imprinted genes located in the locus related to the Prader-Willi syndrome." (PMID 31315906, 2019).
premature aging syndrome (1 paper, 2019). Changes in the organism associated with senescence, occurring at an accelerated rate. "For example, general, conditional, and transient expression of Oct4, Sox2, Klf4, and c-Myc (OSKM) suppressed cellular and physiological hallmarks of aging and prolonged lifespan in a mouse model of HSPG progeria and premature aging syndrome." (PMID 31310235, 2019).
prion disease (1 paper, 2016). A transmissible disease that is caused by a protein that is able to induce abnormal folding of normal cellular proteins, leading to characteristic spongiform brain changes, which are associated with neuronal loss without an inflammatory response. "Brain expression levels of neuronal progenitor markers, nestin (Nestin), sex determining region Box 2 (Sox2), Class III beta-tubulin (Tuj1) decreased towards end-stage prion disease whereas doublecortin (Dcx) levels were less affected." (PMID 27886261, 2016).
psoriasis (1 paper, 2015). An autoimmune condition characterized by red, well-delineated plaques with silvery scales that are usually on the extensor surfaces and scalp. "Psoriasis-like changes in DEGP expression were also observed in fibroblasts transduced with OKSM reprogramming factors (OCT4, KLF4, SOX2, c-MYC), demonstrating pathway-level overlap between psoriasis and induced pluripotency." (PMID 26251673, 2015).
relapsing-remitting multiple sclerosis (1 paper, 2018). The most common clinical variant of multiple sclerosis, characterized by recurrent acute exacerbations of neurologic dysfunction followed by partial or complete recovery. "Another group established an hiPSC cell line from fibroblasts isolated from a patient with relapsing-remitting multiple sclerosis (MS) by retroviral transduction using OCT4, SOX2, KLF4 and c-MYC factors (MSiPS)." (PMID 29439516, 2018).
renal fibrosis (1 paper, 2024). A final common manifestation of a wide variety of chronic kidney diseases characterized by glomerulosclerosis and tubulointerstitial fibrosis. "USC-Exos reduce renal fibrosis and inflammation by activating the PI3K-AKT and MAPK pathways through the miR-122-5p/SOX2 axis derived from USC-Exos." (PMID 38617751, 2024).
retinal (1 paper, 2024). "Although Sox2 has not been shown to directly promote axonal regeneration, the involvement of Sox2 in Müller glia-derived neuron replacement indirectly implicates Sox2 in potentially forming new axons from regenerated neurons in response to retinal damage." (PMID 38882059, 2024).
retinal diseases (1 paper, 2023). "In conclusion, our results showed that SOX2‐positive RSCs are present in the pars plicata and may be valuable for treating human retinal diseases due to their proliferation and differentiation potential." (PMID 36582303, 2023).
retinitis pigmentosa (1 paper, 2025). Retinitis pigmentosa (RP) is an inherited retinal dystrophy leading to progressive loss of the photoreceptors and retinal pigment epithelium and resulting in blindness usually after several decades. "Indeed, PROX1 was accumulated in SOX2-positive MG of 79 years-old retinitis pigmentosa (RP) patient retina but not in the MG of 83 years-old healthy donor retina." (PMID 40133314, 2025).
schizencephaly (1 paper, 2010). "Analysis of sequencing of the LHX2, HESX1, and SOX2 exons and exon–intron junctions in 97 cases of schizencephaly did not reveal mutations that were likely to be pathogenic." (PMID 20949537, 2010). "Because of the overlap sometimes observed between schizencephaly and SOD, we also hypothesized that genes associated with SOD—HESX1 and SOX2—might also cause some cases of schizencephaly." (PMID 20949537, 2010).
serous cystadenocarcinoma (1 paper, 2017). A malignant serous cystic neoplasm usually involving the ovary or the pancreas. "In over 50% of cases of serous cystadenocarcinoma, SOX2 was expressed in > 75% of the cells of the tissue examined, whereas in only 5% of cases of less severe serous cystadenoma was SOX2 expressed in > 75% of the cells." (PMID 28388544, 2017).
serous papillary adenocarcinoma (1 paper, 2011). "We report the presence of SSEA-4, SOX-2, VASA and ZP2-positive primitive oocyte-like cells in the adult ovarian surface epithelium of a patient with serous papillary adenocarcinoma." (PMID 21827672, 2011).
silicosis (1 paper, 2025). Silicosis is a respiratory disease caused by breathing in (inhaling) silica dust. "In the silica-treated mouse model of silicosis, researchers found that SOX9 and SOX2 are markers of embryonic lung stem/progenitor cells." (PMID 39974732, 2025). "During the early inflammatory phase of silicosis, SOX9 and SOX2 were re-expressed in the distal lung and exhibited abnormal distribution." (PMID 39974732, 2025).
skin papilloma (1 paper, 2020). A benign papillary neoplastic growth on the skin composed of epithelial cells and a fibrous stalk. "Similarly, lineage ablation of SOX2+ tumor cells and conditional deletion of SOX2 in pre-existing skin papilloma and SCC could cause tumor regression." (PMID 30517668, 2020).
soft tissue tumors (1 paper, 2023). "In addition to the traditional immunohistochemical markers that are applied for diagnosing SS, we also explored the diagnostic value of a panel of markers that have recently been used in other soft tissue tumors, such as SOX-2, PAX-7, NKX3.1 and INI-16,16–19." (PMID 37193761, 2023).
spindle cell carcinomas (1 paper, 2022). "Silencing TNFR1 in SCC cells inhibits cell proliferation, reduces UBCH10, Twist1, Sox2, and c-Myc levels, converts spindle cell carcinomas into well-differentiated SCCs, dampened tumor burden, and blocked metastasis." (PMID 36270982, 2022). "When injected via tail vein, KALLU+ lung SCC cells that highly expressed TNFR1/TNF, Sox2, c-Myc, Twist1, Bcl2, and UBCH10, generated dedifferentiated spindle cell carcinomas with epithelial–mesenchymal transition markers in mouse lungs." (PMID 36270982, 2022).
squamous cell tumors (1 paper, 2010). "However, they may relate to differences between tumor types included in the datasets: SOX2 may play different roles in squamous cell tumors and adenocarcinomas." (PMID 20548776, 2010).
steatosis (1 paper, 2012). Increased lipid within the cytoplasm of cells. "Retroviruses encoding the reprogramming factors, OCT4, SOX2, KLF4, and c-MYC were transduced into fibroblasts cells from patient with steatosis (H0008) and control (H0002) using well established protocols." (PMID 22969728, 2012).
subarachnoid hemorrhage (1 paper, 2015). A serious neurological disorder characterized by intracranial hemorrhage into the subarachnoid space. "In human brain following subarachnoid hemorrhage excised cortex had upregulated mRNA expression of Sox2 and Musashi2 as evaluated by PCR, in tandem with other markers of proliferation; this was matched by immunohistochemical detection of Musashi2 in tandem with the proliferation marker Ki67." (PMID 25713758, 2015).
temporal lobe epilepsy (1 paper, 2020). A localization-related (focal) form of epilepsy characterized by recurrent seizures that arise from foci within the temporal lobe, most commonly from its mesial aspect. "Moreover, effective inhibition of neuronal apoptosis provided a neuroprotective effect by the up-regulation of Bcl-2, Bcl2l1, Bdnf, Sox-2, and NeuroD1 genes in an animal model of temporal lobe epilepsy." (PMID 32982679, 2020).
testicular embryonic carcinoma (1 paper, 2020). "NCCIT cells are testicular embryonic carcinoma with similar gene expression profiles to embryonic stem cells, with the abnormal overexpression of core stemness genes, including Nanog, Oct4, and Sox2." (PMID 32650569, 2020).
testicular teratoma (1 paper, 2025). "In 129/SvJ Dnd1Ter/+ mice, acute foetal hypoxia (10% O2 for 12 h at E13.8–E14.3) increased bilateral testicular teratoma frequency from 3.3% to 64% and preserved OCT4/SOX2/NANOG expression as well as TGF-β family morphogen (Nodal) activity." (PMID 41582951, 2025).
thoracic neoplasms (1 paper, 2024). "In the setting of thoracic neoplasms, it has been described that SMARCA4 loss correlates with poorer outcome and expression of SOX2, CD34, and SALL4, and SMARCB1 loss is mainly seen in thoracic neoplasms of a mesenchymal lineage." (PMID 39125735, 2024).
thyroid tumor (1 paper, 2021). A benign or malignant neoplasm affecting the thyroid gland. "Nevertheless, these observations collectively suggested that the Shh pathway promotes SOX2 and BMI1 expression in thyroid tumor cell lines." (PMID 33499351, 2021).
transient cerebral ischemia (1 paper, 2019). "In the present study, a retroviral solution (1.5–2.0 × 107 /ul) of mock pMX-GFP (n = 13) or pMX-Ascl1/Sox2/NeuroD1 (ASN) (n = 14) was directly injected into the ipsilateral striatum and cortex 3 days after 30 min of transient cerebral ischemia." (PMID 31358888, 2019).
type 2 diabetes (1 paper, 2023). "Furthermore, in vivo data revealed that treatment with cisplatin or metformin—a mitochondrial complex inhibitor and conventional therapy for type 2 diabetes—reduced IL-1RA-associated xenograft tumor growth as well as EGFR/JNK activation and SOX2 expression." (PMID 37461111, 2023).
vascular malformation (1 paper, 2023). A non-neoplastic disorder that is the result of defects of vascular morphogenesis. "A non-exhaustive list, including procollagen-lysin, 2-oxoglutarate 5-dioxygenase 2 (PLOD), KRASG12V, Ras/MAPK, Wnt, BMP/TGF- β, and Sry-box 2 (SOX2), likely contribute to de novo vascular malformations in the carotid circulation." (PMID 37153271, 2023).
verrucous carcinoma (1 paper, 2023). A well differentiated squamous cell carcinoma characterized by a papillary growth pattern, acanthosis, mild cytologic atypia, and pushing tumor margins. "In one study, it was reported that ALDH1 and Notch1 were uncommonly detected in verrucous carcinoma, whereas in another, the significantly increased expression of ALDH1 and SOX2 is associated with verrucous carcinoma." (PMID 37303447, 2023).
visual disorders (1 paper, 2015). "Likewise, Sox2 mutations were recently reported to be associated with visual disorders." (PMID 25578969, 2015).
tumor (2,035 papers, 2007 to 2026). "Our findings demonstrate the different susceptibility of basal populations to cSCC transformation and reveal that SOX2 renders the otherwise tumour-resistant progenitor population susceptible to oncogenic transformation." (PMID 41507151, 2026). "Among stemness-associated transcription factors, OCT-4 and SOX-2 are key regulators of pluripotency and stem cell maintenance and have been implicated in cancer stem cell biology and tumor progression." (PMID 42232802, 2026). "One model employs a Brd4::hNUTM1 knock-in allele activated by the FLEx system and Sox2-CreERT2, resulting in widespread fusion expression and consistent tumor formation in the esophagus, including the gastroesophageal junction." (PMID 41266112, 2026). "Key outcomes include reduced tumor burden and modulation of molecular markers associated with tumor stemness (SOX2), immune evasion (PD-L1, IDO), cellular proliferation (Ki67), and chemoresistance (MGMT)." (PMID 41596406, 2026). "Combined siSOX2 and cisplatin treatment inhibits tumor progression in vitro, with low SOX2 expression linked to better patient survival." (PMID 41268614, 2026). "In contrast, tumors that arise from SOX2-negative lineages ectopically activate SOX2 during tumor progression, particularly in association with squamous transdifferentiation, but its functional contribution in these contexts appears variable or non-essential." (PMID 41266112, 2026). "It was postulated that overexpression of SOX2 induces cancer stemness, tumor invasion, and drug resistance and is associated with poor survival in different types of cancers." (PMID 41189680, 2026). "In a complex review study, it was demonstrated that SOX2 is expressed in at least 25 types of cancer and directly implicated in tumor aggressiveness." (PMID 41012776, 2025). "In frozen patient samples, CHI3L1 and osteopontin immunostainings were significantly more intense in tumor samples than in control brainstem, and they were associated to SOX2+ cancer cells." (PMID 40703808, 2025). "While some studies associate Sox-2 overexpression with increased tumor aggressiveness and poor prognosis, others suggest the opposite." (PMID 40069421, 2025). "Initially, the association of YAP and TAZ with SOX2 was re-validated by isolating the CD44+/CD24− cell population from patient tumor samples." (PMID 39979255, 2025). "Briefly, TGIF2 overexpression was closely associated with T stage (P=0.011), lymph node metastasis (P=0.032), and TNM stage (P=0.028), whereas SOX2 overexpression was associated with tumor size (P=0.029) and T stage (P=0.026)." (PMID 39781447, 2025). "Consistently, there was markedly reduced Ki-67 expression, indicative of decreased proliferation of Sox2-deficient tumor cells in Lcre;NICD1;Sox2cko mice." (PMID 40128799, 2025). "Multiple studies have shown that tumor-associated macrophages (TAMs) can directly influence the expression of cancer stem cells (CSCs) and their markers, specifically regulating SOX-2." (PMID 40011711, 2025). "Research indicates that the levels of SOX2 dosage are significantly associated with both the advancement of tumor cells and their dormant state." (PMID 39976818, 2025). "High SOX2 expression has been associated with an undifferentiated state, a condition that enables tumor cells to proliferate indefinitely." (PMID 40699660, 2025). "In patients, elevated SOX2 expression in CRC has been associated with advanced tumor grade, TNM (tumor, node, metastasis) stage, metastasis, and poor patient survival." (PMID 40179020, 2025).
tumor (continued). "In tumours, high expression of SOX2 is closely associated with tumour recurrence, treatment resistance and poor prognosis." (PMID 40665579, 2025). "SOX2, a stemness-associated transcription factor, correlates with tumor cell plasticity and proliferative potential." (PMID 41333228, 2025). "Regarding prognosis, E2F1 expression was associated with age, gender, smoking, stage, and tumor size, whereas MYC correlated with smoking, tumor size, and metastasis, and SOX2 was only associated with lymph node metastasis." (PMID 40886002, 2025). "The pluripotency of cancer stem cells, crucial for tumor persistence and recurrence, is strongly linked to the SOX2 (SRY-Box Transcription Factor 2) and HOXA9 (Homeobox A9) TF families." (PMID 41155227, 2025). "As a result, 52 of the 413 SOX2-bound genes were identified, the expression of which was significantly reduced in Sox2-deficient tumor cells." (PMID 40128799, 2025). "Sox2 and c-Myc have been identified as the downstream target genes of the Hippo signaling pathway, which has been linked to tumor progression when dysregulated." (PMID 40332113, 2025). "To strengthen the case for the functional role of Sox9 loss to increased SOX2 levels and tumor progression, we studied how Sox9 genetic inactivation affected the AKP model and the tumors arising (termed AKPS tumors)." (PMID 40179020, 2025). "Our findings provide a notable contrast to the prevailing literature, which often associates high expression of pluripotency-associated transcription factors (NANOG and SOX2) with increased metastatic potential in tumor cells." (PMID 40227667, 2025). "The authors revealed that SOX2 overexpression was associated with aggressive pathological features, including a high tumor stage and grade, sessile architecture and the presence of glandular differentiation." (PMID 39272712, 2024). "SOX2 overexpression is associated with increased tumor growth and resistance to differentiation, highlighting its significance in GBM pathogenesis." (PMID 39063221, 2024). "KYNU expression was correlated with the expression of tumor stemness-associated factors (SOX2, Nanog, and OCT4) and the tumor size." (PMID 38577600, 2024). "Overexpression of SOX2 is associated with increased tumor growth and resistance to differentiation, highlighting its role in GBM pathogenesis." (PMID 39063221, 2024). "Genes like APOBEC3B, APOBEC3C, and YTHDC1, highly expressed in tumor cells, were linked to tumor stemness and correlated with markers such as SOX2 and BM1." (PMID 39409886, 2024). "OCT4, Nanog, and SOX2 are critical regulators of pluripotency and self-renewal and are known to be associated with poor clinical outcomes due to their role in promoting tumor-initiating cells." (PMID 39768178, 2024). "This analysis shows that active Notch signaling and high levels of SOX2 can coexist within the same tumor, and associates with poor prognosis, similar to patients whose TNBC tumors express a NotchHigh signature only or SOX2 only." (PMID 39478150, 2024). "We also observed increased expression of neural stem/progenitor markers like SOX2 in all the LEGOs, indicating differentiation blockage upon loss of tumor suppressors, consistent with staining." (PMID 38273014, 2024). "We identified a reciprocal inhibitory feedback mechanism between Notch signaling and the pluripotent associated stem cell (SC) transcription factor (TF) SOX2, which shapes tumor cell plasticity and associated therapeutic response to GSI." (PMID 39478150, 2024). "Here, we identify and mechanistically describe a reciprocal inhibitory feedback loop between Notch signaling and the SC-associated TF SOX2, that regulates tumor cell plasticity and associated therapeutic response in NOTCH-driven TNBC." (PMID 39478150, 2024). "A large number of studies in the literature have highlighted the important role of SOX2 in promoting GBM malignancy and the association of high SOX2 levels with tumour aggressiveness and poor clinical outcome." (PMID 38267500, 2024).